MIDEAS (mitotic deacetylase associated SANT domain protein)
Synonyms: C14orf117; C14orf43; ELMSAN1; LSR68; c14_5541
Tractability: PROTAC: UniProt records ubiquitination sites on it; ubiquitination databases record sites on it.
Gene: Protein-coding gene on chromosome 14 (73,715,122 to 73,790,285, reverse strand). Ensembl gene ENSG00000156030.
Subcellular location: Nucleus
Subcellular location (Human Protein Atlas): Nucleoplasm
Gene Ontology:
Molecular function: protein binding; transcription corepressor activity
Biological process: chromatin organization; negative regulation of DNA-templated transcription; regulation of embryonic development; regulation of transcription by RNA polymerase II
Cellular component: histone deacetylase complex; nucleoplasm; transcription regulator complex; nucleus
Genetic constraint (gnomAD): Loss-of-function variants: 27 observed, 99.57 expected, observed/expected ratio (o/e) 0.27, 90% interval 0.2 to 0.37. The upper end of that interval is the gene's LOEUF score, 0.37, which puts it in group 1 of 6, group 1 being the genes least tolerant of losing a copy. Missense variants: 1,231 observed, 1,424.6 expected, observed/expected ratio (o/e) 0.86, 90% interval 0.82 to 0.91. Synonymous variants: 585 observed, 591.92 expected, observed/expected ratio (o/e) 0.99, 90% interval 0.92 to 1.06.
Homologues: Orthologues: chimpanzee MIDEAS (99% identical), macaque MIDEAS (98% identical), dog MIDEAS (92% identical), pig MIDEAS (91% identical), guinea pig MIDEAS (88% identical), mouse Mideas (85% identical), rat Mideas (84% identical), rabbit MIDEAS (82% identical), tropical clawed frog mideas (48% identical), zebrafish mideasb (38% identical), zebrafish mideasa (31% identical), Caenorhabditis elegans saeg-1 (15% identical), and 5 more. Paralogues in human: TRERF1 (27% identical), ZNF541 (23% identical), RCOR2 (8% identical), RCOR3 (8% identical), RCOR1 (7% identical).
Diseases named in the same sentence as MIDEAS in open-access papers:
MIDEAS is named in the same sentence as 8 diseases in open-access papers, as found by Europe PMC text mining. Sharing a sentence is not in itself a finding about the gene and the disease. The quoted sentences say what the papers report.
myeloid leukemia (1 paper, 2024). A clonal proliferation of myeloid cells and their precursors in the bone marrow, peripheral blood, and spleen. "MiDAC has been shown to contain protein subunits MIDEAS, HDAC1, HDAC2 and DNTTIP1 in myeloid leukemia K562 cells and human T lymphocyte CEM cells." (PMID 38781120, 2024).
neurodevelopmental disorder (1 paper, 2025). A behavioral and cognitive disorder with onset during the developmental period that involves impaired or aberrant development of intellectual, motor, or social functions. "Here we present two unrelated probands with the same de novo MIDEAS variant (NM_001367710.1: c.1961A>C (p.Tyr654Ser)) and overlapping phenotypic features, revealing that MIDEAS is an autosomal dominant monogenic neurodevelopmental disorder gene." (PMID 41290615, 2025).
MIDEAS also shares sentences with these, for which no sentence is quoted: tumor (2 papers); cancer (1); flu (1); Hypertension (1); lung carcinoma (1); non-small cell lung carcinoma (1).